CXCL1 (C-X-C motif chemokine ligand 1)
Diseases named in the same sentence as CXCL1 in open-access papers (continued):
Sharing a sentence is not in itself a finding about the gene and the disease.
tumor (continued). "The expression of CXCL1, CXCL2, CXCL5, and CXCL8, which are CXCR2 ligands, and the expression of KITL and GM-CSF are strongly enhanced by KRAS signaling in cancer cells and tumor-derived hypoxia." (PMID 31474975, 2019). "Our recent study demonstrated a novel role of two chemokines, CXCL1 and CXCL2, in promoting monocytic MDSCs (mo-MDSCs) generation by favoring the differentiation of bone marrow cells under tumor conditions." (PMID 31395859, 2019). "Production of CXCL1 and CXCL8 by a variety of tumor cell types has been shown to be induced by the conditioned media obtained from senescent human peritoneal mesothelial cells." (PMID 30870978, 2019). "These cells express CXCR1 and CXCR2 at their surface and are recruited by their ligands including CXCL1 and CXCL2 which can be produced by tumor, endothelial cells or fibroblasts." (PMID 29983866, 2018). "Corresponding with our results of enhanced anchorage-independent growth, CXCL1 also increased the expression of CD44, CD326 and CD133, well-known cancer stem cell markers in tumor spheroids." (PMID 30115896, 2018). "One of the central signals in the TME that induces the pro-tumor TAN phenotype appears to be TGFβ, which induces the expression of CXCL1, VEGF, and MMP9, which are all factors leading to a more persistent tumor growth." (PMID 30349530, 2018). "In the STING agonist-treated tumour-bearing mice, we foundsignificantly elevated levels of the cytokines, CXCL10, CCL5, IFN-γ, M-CSF, CXCL9and CXCL1 at early, mid and late time points in comparison to levels in plasmafrom vehicle-treated mice." (PMID 30046165, 2018). "Here, we focused on CXCL1 and CXCL2, which function as chemokines to attract MDSCs to the tumor, since Snail knockdown attenuated intratumoral MDSC which suppressed CD8+T cell proliferation." (PMID 29703902, 2018). "Neutrophils are recruited at the tumor sites by several chemokine signals, such as CXCL12, CXCL8, CCL3 (MIP-1α), and CXCL6 (huGCP-2), or murine chemokines CXCL1, CXCL2, and CXCL5." (PMID 30591657, 2018). "Snail knockdown reduces the expression of CXCR2 ligands (CXCL1 and CXCL2), chemokines that attract MDSCs to the tumor via CXCR2." (PMID 29703902, 2018). "Similar to MDSCs, TAMs and TANs are recruited to tumor sites by tumor-derived chemokines and growth factors, including CCL2/MCP-1, CXCL1/Gro-a, CCL7/MCP-3, CCL5/RANTES, CXCL8/IL-8, VEGF, PDGF, and M-CSF/CSF-1." (PMID 29735917, 2018). "IKKα is further shown to critically mediate IL-1β signaling in KRAS-mutant tumor cells, culminating in marked MPE-promoting effects delivered by C-X-C chemokine motif ligand 1 (CXCL1), and in oncogenic addiction with mutant KRAS evident as drug resistance." (PMID 29445180, 2018). "Because it has been reported that the tumour‐derived factors such as CCL2, SDF1, IL6, TNFα, VEGF, G‐CSF, TGFβ, and CXCL1 function in the pre‐metastatic phase, we applied those factors to HepELs in the tumour‐bearing mouse liver in vitro." (PMID 29930175, 2018). "Remarkably, the stromal and tumor expression of CXCL2, together with CXCL1, is regulated by the exposure to pro-inflammatory cytokines, such as TNF-alpha." (PMID 30591657, 2018). "RNA sequence analysis of myeloid-driven tumorigenic BPH-TW cells revealed increased expression of IL-1α and its target genes CXCL1 and CXCL8. shRNA knockdown of IL-1α in the transformed BPH-TW tumor cells resulted in decreased tumor growth." (PMID 29502208, 2018). "In conclusion, Snail upregulates the expression of CXCL1/2 and enhance MDSC tumor infiltration via CXCR2; MDSCs were shown to inhibit anti-tumor immunity and promote tumor progression." (PMID 29703902, 2018). "Expression of the CXCR2 ligands CXCL1 and CXCL2, known to be downstream of MAPK and NF-κB signaling, correlated with accumulation of CXCR2 positive gMDSC in the TME with tumor progression." (PMID 28915554, 2017).
tumor (continued). "TAM derive from circulating monocytes, which are recruited into the substance of the tumor by a wide range of chemokines, especially MCP-1/CCL2, CXCL1, CXCL10 and SDF-1/CXCL12, released either by tumor cells or other stromal cells." (PMID 28098760, 2017). "Together suggest that while IRISOE tumor cells secrete low-level CCL2 under normal condition, hypoxia and/or MSCs contact through the IL-1β/CXCL1 circuit exacerbates CCL2 secretion from these cells." (PMID 29262555, 2017). "Among these differentially expressed genes, pro-inflammatory cytokines, such as IL6, CXCL1, CXCL5, CXCL8, and CSF2 were further validated as significantly downregulated in WCE-treated PC-3 and DU145 tumor tissues." (PMID 29142311, 2017). "Addition of IL-1β NeuAb before MSCs contact (yellow bars), or CXCL1 NeuAb after MSCs (green bars) abrogated that increase in VEGF secretion from IRISOE tumor cells." (PMID 29262555, 2017). "CXCL1, CXCL5 and CXCL8 were overall the most abundant chemokines present in the RCC tumor supernatants." (PMID 28923105, 2017). "In gene expression arrays, the overexpression of TLR4 in tumor cells correlated with gene expression of ATF-3, IL-6, CDH13, CXCL-1 and TFPI." (PMID 28982115, 2017). "Collectively the reduced levels of CXCL-1 and CCL5 argue that the direct and indirect stimulation of tumor cell growth by immunological factors and the immune system is reduced in tumors previously exposed to [curcumin + sildenafil]." (PMID 29245915, 2017). "When 500 ng/ml CXCL1 antibody or 400 nM CXCR2 inhibitor SB225002 was added into CAF medium, SOD1 was significantly upregulated in tumor cells, suggesting CAF-secreted CXCL1 inhibited the expression of SOD1." (PMID 28518141, 2017). "We detected a concentration gradient for the CXCR2 ligands CXCL1, CXCL2, CXCL5, CXCL6 and CXCL8 between the plasma and the tumor tissues of patients with primary RCC." (PMID 28923105, 2017). "Together suggest that while IRISOE tumor cells secrete low-level VEGF under normal condition, hypoxia and/or MSCs contact through the IL-1β/CXCL1 circuit exacerbates VEGF secretion from these cells." (PMID 29262555, 2017). "Most ELR+ CXC chemokines, including CXCL1–3 and CXCL5–8, increase the tumor tissue penetration of immunosuppressive cells, reduce apoptosis, and promote angiogenesis as well as tumor cell proliferation, migration, and invasion by activating the CXCR2 receptor." (PMID 29312644, 2017). "Plasma levels of tumor-derived human IL6 and CXCL1 were indeed ablated in WCE-treated mice compared to vehicle-treated mice." (PMID 29142311, 2017). "Together suggest that IL-1β secreted by IRISOE tumor cells recruits MSC into tumors’ aggressiveness niche, activates them to secrete CXCL1, which entrains IRISOE tumor cells to secrete higher local and systemic levels of CCL2 and VEGF, in vivo." (PMID 29262555, 2017). "Among these, CXCL1, CXCL5, and CXCL8 have been described to stimulate PCa cell proliferation, cell survival, migration, invasion, and angiogenesis, thus promoting tumor growth as well as metastasis." (PMID 29142311, 2017). "When KYSE-30 and KYSE-150 were cultured in CAFs medium, which contained 500 ng/ml CXCL1 antibody, the radioresistance of tumor cells was significantly reversed, suggesting CAF-secreted CXCL1 was responsible for tumor radioresistance." (PMID 28518141, 2017). "GRO chemokines that are expressed during melanoma tumours, and are essential for wound healing activities, comprise three highly similar proteins known as GRO-α (CXCL1), GRO-β (CXCL2) and GRO-γ (CXCL3)." (PMID 28989790, 2017). "CCL2, CCL3, CCL4, CCL5, CXCL1, CXCL8 etc. are chemokines involved in the recruitment of MDSC to tumour microenvironment." (PMID 28275390, 2017). "We next measured whole tumor RNA levels of the chemokine receptors CXCR2 and CSF1R as well as the cognate chemokines for these receptors, CXCL1/CXCL2 and CSF1, respectively." (PMID 28915554, 2017).
tumor (continued). "Together suggest that IL-1β secreted by IRISOE tumor cells activates MSCs in a paracrine fashion to secrete CXCL1, which also in a paracrine fashion activates IRISOE tumor cells to secrete CCL2." (PMID 29262555, 2017). "3xTg-AD mice had an increased pro-inflammatory response characterised by the production of pro-inflammatory mediators such as tumour necrosis TNF-α, IL-6, CCL5 and CXCL-1, as well as an increase in immune cell infiltration to the sites of infection." (PMID 28284226, 2017). "In concert with CXCL1, S100A8/9 and IL-8 entrain IRISOE tumor cells to survive the harsh conditions within the niche (step 5) to become metastatic precursors." (PMID 29262555, 2017). "Consistent with patterns of heavy Ly6Ghi gMDSC infiltration, MOC1 tumors expressed increased transcript levels of CXCR2 and the CXCR2 ligands CXCL1 and CXCL2, with a significant increase in expression between days 10 and 20 of tumor progression." (PMID 28915554, 2017). "It is recruited to the tumour microenvironment by chemokines such as CXCL8,CXCL1,CXCL2, and CXCL3 by the production of inflammatory mediators such as TNF-Alfa, MIP-1 ALFA, H202, and NO that are cytotoxic to tumour cells." (PMID 28275390, 2017). "Meanwhile, miR-200a plays an anti-tumor role in HCC progression, in part by repressing CXCL1 expression." (PMID 27542259, 2016). "Recently, it has been reported that stably silencing of CXCL1 can inhibit tumor growth in HCC, and knocking down of CXCL1 expression can inhibit tumor growth in colorectal liver metastasis." (PMID 27446967, 2016). "Expression of CXCL1 and CXCL2 in blood and tumor was significantly higher in Ifnb1−/− mice as compared to wild-type (WT) controls." (PMID 28066438, 2016). "CXCL1, CXCL2, and CXCL3 expression was higher and CXCR1 expression was lower in tumor tissues during HCC progression compared with the controls." (PMID 27682863, 2016). "We found that CXCL1 regulates mitochondrial metabolism, autophagy, and EMT pathways, all of which play crucial roles in tumor proliferation and invasion." (PMID 27542259, 2016). "Low CXCL1 or CXCL2 level in BM and high level of these chemokines in the tumor form gradient in tumor-bearing mice, thus attracting neutrophils into tumor site." (PMID 28066438, 2016). "Specifically, the chemokine‐related genes, CXCL1, CXCL2, CXCL3, and IL‐1β, were up‐regulated, while CXCR1 was down‐regulated in tumor tissue during the progression of HCC." (PMID 27682863, 2016). "We show that obese patients have increased CXCL1 expression in the prostate epithelium, increased systemic ASC mobilization and increased infiltration of CXCR1-expressing cells in the tumour stroma." (PMID 27241286, 2016). "High CXCL1 expression predicted recurrence in HCC patients and promoted tumor progression in both in vivo and in vitro experimental systems." (PMID 27542259, 2016). "Nonparenchymal liver cells, including hepatic stellate cells, hepatic dendritic cells, neutrophils, monocytes, and Kupffer cells, secrete CXCL1 and other chemokines to recruit immune cells and modify the HCC tumor microenvironment." (PMID 27542259, 2016). "Recent studies have shown that several proinflammatory chemokines such as IL-8, CXCL1, and CXCL12 drive cancer progression by facilitating tumor cell growth, survival, and migration as well as by inducing angiogenesis." (PMID 27143385, 2016). "Different from cell culture system where CXCL1 and 2 were enhanced, CCL20 was specifically increased in SKCXCR2-derived tumor tissues compared to SKA-derived tumor tissues." (PMID 27723802, 2016). "High epithelial CXCL1 and high stromal CXCR1 expression was also observed for all tumours from patients with metastasis who were still alive at the time of array assembly (data not shown)." (PMID 27241286, 2016). "Overexpression and binding of CXCL1 and its receptor CXCR2 has been shown to promote tumour invasion." (PMID 27028996, 2016).
tumor (continued). "In contrast to the increase of CCL20 in SKCXCR2-derived tumor tissues in vivo, SKCXCR2 cells in vitro had specific increase in CXCL1/2 through NF-κB signaling compared to SKA cells." (PMID 27723802, 2016). "Blocking receptors for the chemokines CXCL1 and CXCL12 retards tumor growth, reduces invasion, eliminates CSCs, and restores drug sensitivity." (PMID 25871388, 2015). "Various MMPs, inflammatory cytokines, chemokines and angiogenic factors, such as IL6, IL8, CXCL1, RANTES, and VEGF are secreted from tumor cells during EMT." (PMID 26084289, 2015). "The continuous recruitment of neutrophils to the tumor site in response to the presence of neutrophil chemoattractants such as IL-8, CXCL-1 and CXCL-2 in the tumor microenvironment, make TAN capable of regulating tumor growth and metastasis." (PMID 26460736, 2015). "This aggressive phenotype was attenuated in CXCR2 knockout mice, mechanistically linking enhanced NF-κB activity, CXCL1 expression, CXCR2-dependent leukocyte recruitment into the tumor microenvironment and aggressive in vivo phenotype." (PMID 26690220, 2015). "Nevertheless, although late-stage Stat3-deficient tumours failed to respond to an anti-CXCL1 monotherapy, the use of CXCL1 blockers combined with standard chemotherapy or as maintenance therapy could be a reasonable alternative to treat these tumours and it deserves further investigation." (PMID 25734337, 2015). "Tumor-derived CXCR2-ligands (IL-8, CXCL1, CXCL2, and CXCL5) attract MDSCs to the tumor microenvironment and inhibition of CXCR2 profoundly suppresses Gr-1+ leukocyte migration into tumor." (PMID 26078490, 2015). "IL-1β in tumors is typically produced by PSCs, inflammatory and tumor cells, is involved in macrophage recruitment and PSC activation, and both IL-1β and CXCL1 worsen desmoplasia." (PMID 26641266, 2015). "Tumor-derived CXCR2-ligands, CXCL1, CXCL2, and CXCL5, have been known to promote recruitment of MDSCs to the site of tumor or to the premetastatic niche." (PMID 26078490, 2015). "Pharmacological inhibition of CXCL1’s cognate receptor CXCR2 normalizes tumour vascularization and microenvironment and reduces tumour burden." (PMID 25734337, 2015). "We found that mice with DNIIR expression had downregulated levels of CXCL1 and CXCL5 and as a result, fewer CD11b+Gr1+ cells in tumor tissue." (PMID 25280532, 2014). "Different C-C motif ligand-chemokines (CCL) and C-X-C motif ligand chemokines (CXCL), such as CCL2, CCL7, CXCL1 and CXCL6, are also potent stimulators of pro-malignant features, such as tumor cell proliferation, migration and invasion, as well as angiogenesis." (PMID 24887580, 2014). "The anti-tumor effect of TNF-α and/or IFN-γ was augmented by neutrophil chemokine CXCL1, and was attenuated by depleting neutrophils." (PMID 25587026, 2014). "In vivo downmodulation of CXCL-1 reduces the metastatic potential in MDA-MB-231 and enhanced anti-tumor effects of chemotherapy." (PMID 24344116, 2014). "Levels of IGF-I, CXCL1, IL-6, and CCL2 were higher in BALF from tumor-bearing mice than naïve mice 32 weeks after urethane treatment, but VEGF levels were unchanged." (PMID 25505466, 2014). "Chemokines that contribute to immune infiltration into tumor sites and tumor growth include the growth-related (GRO) family of chemokines (CXCL1, 2 and 3) and CXCL8." (PMID 24224100, 2013). "The chemokines CXCL1, -2, -3, -5, and IL8 (CXCL8) were among the top-210 genes that were observed to be upregulated in metastases compared with primary tumours, and they showed highly correlated expression patterns." (PMID 22518090, 2012). "Chemokines such as CXCL1 and CXCL8 are able to enhance tumor cell proliferation; CXCL5 and CXCL12 attract neutrophils and MDSC, while CXCL12 promotes the migration of tumor cells that express the cognate receptor CXCR4." (PMID 22927846, 2012).
tumor (continued). "The secreted interleukin-like Gro-alpha oncogene (CXCL1) and matrix-metalloproteinase 3 (MMP3) promote tumor initiation and growth, while chitinase 3 like-1 (CHI3L1) can protect cancer or/and stromal cells against apoptosis." (PMID 23155391, 2012). "Transcriptome analysis of purified tumor-infiltrating immune cells indicated that only PMN-MDSC express Il8rb (also known as CXCR2), the receptor for CXCL1, CXCL2, and CXCL5." (PMID 21980263, 2011). "Increased secretion of CXCL1 and CXCL8 from tumour epithelium has also been reported to induce angiogenesis in gastro-intestinal cancers." (PMID 21285972, 2011). "We report an increased expression of CXCL1, CXCR1 and CXCR2 in tumour, compared with the surrounding normal epithelium, providing evidence for enhanced autocrine CXC chemokine signalling in these cancer cells." (PMID 21285972, 2011). "In renal cell cancer the levels of CXCL1, CXCL3 and CXCL8 were elevated compared to controls and in receptor negative (CXCR2−/−) mice there was a corresponding reduction in tumour growth." (PMID 21298036, 2011). "The TCM components CCL2, CXCL1, CXCL5 and VEGF seem to play a role in modulating the inflammatory response through inhibition of IL-12p70 secretion by DCs, possibly to protect the tumour from a potent immunologic response against it." (PMID 22125641, 2011). "Understanding the impact of these potential roles of CXCL1 to adverse prognosis merits further studies in CRC collections that include a greater overall number of stage III and/or stage IV tumours." (PMID 21285972, 2011). "Intermediate to strong expression of CXCL1, CXCR1 and CXCR2 was concurrently detected in the epithelium of stage II and stage III CRC tumours." (PMID 21285972, 2011). "Expression of CXCL1, CXCR1 and CXCR2 was elevated in tumour epithelium relative to normal adjacent tissue (P<0.001)." (PMID 21285972, 2011). "Densitometric analysis of the RT-PCR revealed a significant decrease in the expression of CXCL1, CXCL2 (p<0.01) and the CXCR1 receptor (p<0.05) in NSCLC tumour samples compared with normal." (PMID 21298036, 2011). "While it has been reported that CCL2, CXCL1 and CXCL5 are important for tumour growth, proliferation, and angiogenesis, the effect of these chemokines on DCs has not previously been documented." (PMID 22125641, 2011). "Irrespective, the characterisation of CXCL1 and CXCR2 expression in the tumour epithelium provides a functional compensation for the absence of CXCL8." (PMID 21285972, 2011). "Several cytokine mRNAs' (CCL3/MIP-1α, CCL15/MIP-1δ, CXCL1, CXCL5/ENA78, CXCL8/IL8, CXCL9/MIG, CXCL10/IP10) were found to be overexpressed in the tumours while CCL15/MIP-1δ, CXCL5/ENA78 and IL8 mRNAs' were overexpressed in paired normals, as well." (PMID 21092330, 2010). "Some have been shown previously to be of importance for tumor growth, invasion, metastasis and/or chemotaxis, such as Gas6/AXL and CXCL1." (PMID 19558675, 2009). "CXCL1 is also known as growth-regulated oncogene-alpha (GRO-alpha) and is involved in many tumor types as an oncogene." (PMID 19203388, 2009). "In contrast to CXCL6, we demonstrated CXCL1 and CXCL5 mRNA and protein expression to be significantly up-regulated in CRC and CRLM tissue specimens in relation to their matched tumor neighbor tissues." (PMID 18578857, 2008). "CXCR2 chemokine ligands CXCL1, CXCL5 and CXCL6 were shown to be involved in chemoattraction, inflammatory responses, tumor growth and angiogenesis." (PMID 18578857, 2008). "CXCL1 and CXCL5 mRNA expressions were significantly up-regulated in all CRC tissue specimens in relation to the matched tumor neighbor tissues (P < 0.001, respectively)." (PMID 18578857, 2008). "CXCL1 was positively correlated with ETS2, and PLEC was negatively correlated with TUBB2, suggesting that these genes may affect tumor development through synergistic effects." (PMID 41523911, 2026).